MIR330 (microRNA 330)
Synonyms: hsa-mir-330; MIRN330; mir-330
Gene: MicroRNA gene on chromosome 19 (45,638,994 to 45,639,087, reverse strand). Ensembl gene ENSG00000284544.
Gene Ontology:
Biological process: miRNA-mediated post-transcriptional gene silencing
Cellular component: RISC complex
Homologues: Orthologues: chimpanzee ptr-mir-330 (100% identical), macaque MIR330 (98% identical), guinea pig MIR330 (97% identical), pig MIR330 (95% identical), mouse Mir330 (90% identical), rat Mir330 (90% identical).
Diseases named in the same sentence as MIR330 in open-access papers:
MIR330 is named in the same sentence as 5 diseases in open-access papers, as found by Europe PMC text mining. Sharing a sentence is not in itself a finding about the gene and the disease. The quoted sentences say what the papers report.
glioma (1 paper, 2025). A benign or malignant brain and spinal cord tumor that arises from glial cells (astrocytes, oligodendrocytes, ependymal cells). "MIR‐330, acting as a tumor suppressor, regulates pediatric glioma cell proliferation and migration." (PMID 39140252, 2025).
myocardial infarction (1 paper, 2021). Gross necrosis of the myocardium, as a result of interruption of the blood supply to the area, as in coronary thrombosis. "However, in another research, overexpression of MIR‐330 was reported to promote left ventricular remodeling, increase myocardial infarction sizes, and aggravate myocardial ischemia-reperfusion injury during coronary recanalization." (PMID 34938340, 2021).
MIR330 also shares sentences with these, for which no sentence is quoted: acute coronary syndrome (1 paper); myocardial ischemia (1); tumor (1).